XRN2 (5'-3' exoribonuclease 2)
Diseases named in the same sentence as XRN2 in open-access papers (continued):
Sharing a sentence is not in itself a finding about the gene and the disease.
cancer (7 papers, 2019 to 2024). A tumor composed of atypical neoplastic, often pleomorphic cells that invade other tissues. "Collectively, these findings provide mechanistic insights into the sensitivity of XRN2-deficient cancer cells to PARP inhibition and strengthen the underlying translational implications for targeted therapy." (PMID 38339346, 2024). "Here, we delineate the cellular consequences of XRN2 deficiency in cancer cells treated with clinically relevant PARP inhibitors (PARPi) to provide mechanistic insights into the synthetic lethal relationship between XRN2 and PARP1." (PMID 38339346, 2024). "At a mechanistic level, PARP inhibition combined with XRN2 deficiency exacerbates R-loop and DNA double-strand break formation in cancer cells." (PMID 38339346, 2024). "Consistent with our previous findings using several different siRNAs, we also show that XRN2 deficiency in cancer cells hyperactivates PARP1." (PMID 38339346, 2024). "This section comprehensively reviews several key findings about the miRNA-regulatory roles of XRN2 in cancer and its associated clinical potential." (PMID 38689093, 2024). "After evaluating the synthetic lethality and underlying cellular stress responses in cancer cells with XRN2 depletion and PARP1 inhibition, we investigated the cell death pathway employed under these conditions." (PMID 38339346, 2024). "Here, we delineate the molecular consequences leading to the synthetic lethality of XRN2-deficient cancer cells induced by PARP inhibition." (PMID 38339346, 2024). "Taken together, these findings further support the PARPi sensitivity of XRN2-deficient cancer cells presented in this study." (PMID 38339346, 2024). "Our findings emphasize the potential translational significance of targeting XRN2 cancer vulnerabilities via PARPi given that PARP1 inhibition impairs its compensatory role in mitigating cellular stress created by XRN2 loss." (PMID 38339346, 2024). "A variety of cancers showed alterations including mutations, deletions, amplifications in Xrn2 gene." (PMID 32859985, 2020). "XRN2 alterations including copy number variation, expression changes, and mutations are frequent in variety of cancers." (PMID 32859985, 2020). "HNRNPK has been reported to associate with CDK9 and XRN2 in cancer cells to potentially regulate transcription elongation and termination, respectively." (PMID 31519929, 2019). "Furthermore, we observed enhanced replication stress in XRN2-deficient cancer cells treated with PARP inhibitors." (PMID 38339346, 2024). "Moreover, establishing the broader applicability of clinically relevant PARP inhibitors on XRN2-deficient cancer cells is warranted." (PMID 38339346, 2024). "In conclusion, at the molecular level, XRN2 deficiency combined with PARP inhibition in cancer cells exacerbates R-loop formation, elevates the generation of DSBs and replication stress, and consequently drives the activation of caspase-3 to initiate cell death." (PMID 38339346, 2024). "XRN2 alterations (mutations, copy number/expression changes) are frequent in a variety of cancers." (PMID 32859985, 2020). "XRN2 alterations (mutations, copy number/expression changes) are frequent in cancers." (PMID 32859985, 2020). "Some of these alterations could compromise XRN2 function and might render these cancers susceptible to PARP1 inhibition." (PMID 32859985, 2020). "Therefore, defining the cellular function of XRN2 in processes besides RNA metabolism is critical to build a mechanistic understanding of the complex phenotypes that arise after XRN2 deficiency and identify potential avenues for targeting XRN2 vulnerabilities in cancer." (PMID 32859985, 2020). "Enhanced PAR (poly(ADP-ribose)) formation in cancer cells presented here is a direct consequence of increased R-loop formation and subsequent DNA damage instigated by XRN2 depletion." (PMID 38339346, 2024).
cancer (continued). "Collectively, these findings highlight the translational implications of targeting XRN2 cancer vulnerabilities with PARP inhibitors (PARPi)." (PMID 38339346, 2024). "In a similar context, XRN2 has also been investigated in cancers based on its intrinsic exoribonuclease activity." (PMID 38689093, 2024). "Collectively, our study provides mechanistic insights into why XRN2-deficient cells display sensitivity to PARPi and strengthens the notion of targeting XRN2 vulnerabilities in cancer via PARP inhibition." (PMID 38339346, 2024). "Collectively, these data clearly show the potential of various FDA-approved PARPi to sensitize XRN2-depleted cancer cells." (PMID 38339346, 2024). "Another recent study also reported that post-translational modification of XRN2 is important for its ability to prevent R-loop-induced genomic instability in cancer cells." (PMID 38339346, 2024). "Nonetheless, these data strongly suggest that XRN2 vulnerabilities in cancers can be exploited by pharmacological inhibition of PARP1." (PMID 32859985, 2020). "Thus, PARP1 inhibitors could potentially target cancers exhibiting deficiency in XRN2 function." (PMID 32859985, 2020). "Thus, PARP1 inhibition could target cancers exhibiting XRN2 functional loss." (PMID 32859985, 2020). "Indeed, PRMT9 inhibition or expression of XRN2-R946K in AML cells promoted R-loop formation and ATR signaling, which underlies cGAS activation in cancer cells." (PMID 38413714, 2024). "These noticeable results could strongly support the practicality as a therapeutic target of blocking the tumorigenesis-driving factor XRN2 for cancer treatment." (PMID 38689093, 2024). "Many cancers exhibit compromised 5′-3′-exoribonuclease 2 (XRN2) expression." (PMID 38339346, 2024). "In addition, how XRN2 recognizes its target miRNAs involved in specific downstream signaling pathways in cancer should be further investigated." (PMID 38689093, 2024). "Interestingly, XRN2 has been reported to be involved in not only miRNA degradation but also miRNA maturation in human cancer cells." (PMID 38689093, 2024). "A recent study highlights XRN2’s involvement in DNA damage response and replication stress, and provides evidence that XRN2 depletion leads to genomic instability in immortalized fibroblast as well as cancer cells." (PMID 32859985, 2020). "Finally, XRN2 was recently reported to play an important role in the invasiveness of certain cancers, and alteration in its expression correlates with poor survival of cancer patients." (PMID 38339346, 2024). "To further substantiate these findings, we sought to evaluate the effect that XRN2 depletion has on PARP1 activation in A549 and MDA-MB-231 cancer cells." (PMID 38339346, 2024). "Our findings provide a mechanistic understanding of why cancer cells rely on PARP1 when XRN2 is absent and strengthen the translational aspect of targeting XRN2 cancer vulnerabilities using PARP inhibitors." (PMID 38339346, 2024). "Previously, we discovered that the simultaneous absence of XRN2 and PARP1 compromises the survival of non-cancer and cancer cells; however, the underlying cellular stress response remained unknown." (PMID 38339346, 2024).
infection (1 paper, 2011). The state of being infected such as from the introduction of a foreign agent such as serum, vaccine, antigenic substance or organism. "Further analysis of IFIT3 and XRN2 that were found to be up-regulated during infection were validated on the transcriptional level." (PMID 21933386, 2011). "In particular, detection of the modulation of XRN2 protein during RSV infection would have escaped detection in other quantitative proteome studies since total XRN2 protein levels were constant throughout infection." (PMID 21933386, 2011). "In contrast, subsequent immunoblotting experiments in cell extracts using antibodies against the two known isoforms of XRN2 did not confirm an increase in protein levels during infection." (PMID 21933386, 2011).
neurodevelopmental disorder (1 paper, 2025). A behavioral and cognitive disorder with onset during the developmental period that involves impaired or aberrant development of intellectual, motor, or social functions. "The extensive involvement of XRN2 in such complex mechanisms of gene expression regulation, particularly in neuronal cell types, offers possible insights into the vast heterogeneity of ASD and its overlap with other neurodevelopmental disorders." (PMID 40373085, 2025).
XRN2 also shares sentences with these, for which no sentence is quoted: Tourette syndrome (2 papers); colorectal cancer (1); HIV-1 infection (1); malignant melanoma (1); mammary adenocarcinoma (1); metastatic cancers (1); oligodendroglioma (1); oral carcinoma (1); osteosarcoma (1); prostate carcinoma (1); respiratory syncytial virus infection (1).